CD4 (CD4 molecule)
Diseases named in the same sentence as CD4 in open-access papers (continued):
Sharing a sentence is not in itself a finding about the gene and the disease.
metastatic melanoma (continued). "Furthermore, PKC-θ was expressed at low levels in the nuclei of CD4+ human Jurkat T cells and CD8+ T cells isolated from immunotherapy-responsive metastatic melanoma patients." (PMID 35326747, 2022). "Interestingly, in opposed to the WM1617 metastatic melanoma cell line, WM983B-educated moDCs were prone to enhance the IL-10 production of CD4+CD25+ lymphocytes." (PMID 36194602, 2022). "In contrast, circulating anti-Melan A CD4+ T cells producing IL-4 or IL-17 were associated with worse 5-year survival in metastatic melanoma patients, while anti-NY-ESO-1 CD4+ T cells (mainly TNF producers) did not have any impact." (PMID 33546283, 2021). "Therefore, we predicted CD4+T cells, CD8+T cells and exploration of their proportion will be of great value to improve objective response rate for metastatic melanoma treatment." (PMID 33169786, 2020). "Previously, we reported on higher frequencies of PD-1-expressing CD4+ T cells in young, but not old patients with metastatic melanoma, data consistent with the current finding albeit that effects of sex were not documented." (PMID 33292359, 2020). "In this study, we found that ILT2 could be detected on both CD4+ and CD8+ T cells in patients with metastatic melanoma and that ILT2 correlated with FoxP3 expression." (PMID 24829758, 2014). "Another study measured the recruitment of CD4+ cells close to tumor cells in resected metastases following treatment with IFN-α for 0–3 weeks in 26 IFN-treated and 10 untreated patients with regional metastatic melanoma." (PMID 24516470, 2014). "Based on the results of our study, frequencies of circulating CD4+CD26high cells may have predictive implications for outcome after treatment with nivolumab and prognostic implications for metastatic melanoma patients in general, regardless of therapy." (PMID 37170241, 2023). "However, in the context of metastatic melanoma, there are no conclusive studies demonstrating the prognostic significance of CD4+ TIL assessment using histopathology." (PMID 33013886, 2020). "Using TMAs constructed from metastatic melanoma samples (from multiple anatomic sites) and IHC to identify major TIL subsets, it was shown that while higher densities of CD3+ and CD8+ TIL were positively associated with OS, this was not the case for CD4+ TIL." (PMID 33013886, 2020). "Thus, it was inferred from above data that CAH (+) treatment might promote the proliferation of CD4+CD8+ double positive T subsets and boost a systemic and durable immune defense against metastatic melanoma." (PMID 30886812, 2019). "Subcutaneous injection of B16shR-SOCS1 cells in CD4 T-cell KO and WT mice promoted otherwise, a significant reduction of lung metastatic nodules, suggesting that SOCS1-silencing elicits a protective immune response against metastatic melanoma mediated by CD8+ T-cells." (PMID 28079159, 2017). "In humans, a single infusion of clonal NY-ESO-1-specific CD4 T cells in a metastatic melanoma patient resulted in complete resolution of pulmonary and nodal disease 2 months after ACT, suggesting that CD4 T cells alone were sufficient to trigger tumour elimination." (PMID 35572552, 2022).
multiple myeloma (72 papers, 2004 to 2025). "Furthermore, basophils, the CCR5+ EM3 CD4 and CD28+ EM5 CD4 subsets were increased in AL amyloidosis compared to MM." (PMID 31462637, 2019).
leukopenia (71 papers, 2010 to 2026). "In the multivariate analysis, only female sex and CD4+ count < 200 cell/ml were strong factors independently associated with leukopenia." (PMID 33170905, 2020). "The difference in patient survival was unexpected, but divided-dose rATG associated with more severe and prolonged CD4 leukopenia, which correlated with multiple and more severe infections." (PMID 26465152, 2015). "In the present study, LA was also upregulated, which might be the cause of hypoalbuminemia, leukopenia, lymphocyte damage, and loss and dysfunction of CD4 T cells in thyrotoxicosis mice." (PMID 35720307, 2022). "Another contributing factor may be the severe leukopenia caused by the virus, with a significant decrease in the number of CD4 and CD8 lymphocytes and elevation of interleukins (IL-2R, IL-6, IL-10, TNF-alpha) and other inflammatory markers." (PMID 35205852, 2022). "Furthermore, we found that severe leukopenia was strongly linked to malnourishment, affecting the numbers of all the white cell subsets, including CD4+ T lymphocytes and B cells." (PMID 24586759, 2014). "Laboratory findings indicating severe pancytopenia, leukopenia, low CD4 count, elevated alkaline phosphatase, total bilirubin, and impaired renal function." (PMID 40755707, 2025). "Previous studies have demonstrated that PMGS ameliorates leukopenia by inhibiting CD4+ T-cell apoptosis and plays critical roles in repressing HPV." (PMID 37233453, 2023). "Corticosteroid-induced immunosuppression induces leukopenia, inhibits phagocytosis, and decreases antigen presentation capabilities, while depletion of CD4+ T cells ablates circulating CD4+ lymphocytes." (PMID 35615354, 2022). "This leukopenia resulted from significant reductions in granulocytes and B-lymphocytes as well as CD4- and CD8-positive T cells." (PMID 35042529, 2022). "CARD11(E626K)CD4-Cre;HBZ Tg mice exhibited leukopenia and a decreased number of CD4+ T cells in peripheral blood." (PMID 36446869, 2022). "CD4+ T transcriptomic cluster 2 was positively associated with age at diagnoses, SLEDAI score, and ACR leukopenia." (PMID 33883687, 2021). "In the present study, leukopenia were significantly increased as the CD4 T cell count decreased and age of HIV infected patients increased, which is in agreement with other studies." (PMID 32931523, 2020). "Only slight leukopenia and a lower level of CD4+ T cells were observed when compared with uninfected chimpanzees." (PMID 22984489, 2012). "HBZ Tg mice exhibited leukopenia and a decreased number of CD4+ T cells in peripheral blood." (PMID 36446869, 2022). "Laboratory examinations revealed leukopenia and a CD4 cell count of 280 cells / mm3." (PMID 34466488, 2019). "The quantitative decrease of Treg was proportional to the degree of leukopenia and somewhat more notable than the reduction in the number of lymphocytes and all CD4+ T cells, which is evident in the graphs with the absolute number of cell populations in the peripheral blood of MDS patients." (PMID 30405716, 2018). "The QJSB group exhibited lower levels of CYTC expression and reduced Caspase-3 activation compared to the CTX-treated group, indicating that QJSB may effectively regulate the mitochondrial pathway and prevent cell death in CD4+ T lymphocytes, ultimately improving leukopenia." (PMID 39295929, 2024). "Building upon the multilayer module network constructed, we identified key targets of CB herbs in the treatment of leukopenia, including TGFB1, C1R, CD4, and HMGB1, which regulate leukopenia through signal transduction, cellular process, and immune response." (PMID 40890790, 2025). "Our results indicated that adjuvant SFI CT is beneficial for outcome indicators such as response rate, KPS score, CD3+, CD4+, CD4+/CD8+, NK cells, leukopenia, and gastrointestinal reactions in patients with BC." (PMID 38212731, 2024).
leukopenia (continued). "The combination of Astragalus polysaccharide for injections and radiotherapy (1 RCT) or palliative chemotherapy (1 RCT) improved the leukopenia and increased the level of CD3, CD4, and CD4/CD8." (PMID 34025425, 2021). "The funnel plots were symmetrical for 12- and 24-month OS, and CD4+, CD8+, CD4+/CD8+ and leukopenia, but were asymmetrical for ORR, DCR and QIR." (PMID 31872855, 2020). "Several major lymphocyte subsets in blood followed the observed leukopenia in E. coli O157:H7 infected pigs, namely total (CD79α+) B cells, total (CD3+) T cells and CD4+ (CD3+) T cells." (PMID 28559930, 2017). "Although this patient had low CD4 counts (<200 cells/mm3), the peripheral WBC counts showed only mild leukopenia." (PMID 26879928, 2016). "There was a relative decrease in size of the CD45RA− CD4+ and CD8+ TCM and TEM populations between 0 and 9 d.p.i., suggesting that leukopenia was related to depletion of MV-infected cells." (PMID 22952446, 2012). "The effects of bendamustine on lymphocytes are lasting leukopenias and low CD4+ counts for 7–9 months as well as negative effects on proliferation of CD3+ cells." (PMID 40728217, 2025). "Severe protein-energy malnutrition also mediates atrophy of the thymus and peripheral lymphoid organs, inducing leukopenia, lower CD4/CD8 ratio, more CD4 and CD8 double-negative T cells, and immature T cells in peripheral blood." (PMID 36248906, 2022). "Other studies reported that intravenous injection of large doses of adenovirus caused leukopenia in non-human primates, humans and hamsters, with a significant decrease in the number of CD3+, CD4+ and CD8+ cells at 1 day post-challenge." (PMID 28270104, 2017). "The leukopenia observed in HLH patients can be attributed to the excessive immune activation and cytokine storms that are hallmarks of the disease, and we noted in our study that the percentage of CD4+ T cells decreased in the EBV-HLH patients when compared with healthy controls." (PMID 40732748, 2025). "The nadir of CD4 count prior to the start of treatment of HCV was not included, as it is possible that the nadir CD4 count drawn during treatment may be confounded by IFN induced leukopenia." (PMID 25688301, 2015). "Moreover, as a result of protein-energy malnutrition, the thymus and peripheral lymphoid organs atrophy, which causes leukopenia, a drop in the CD4/CD8 ratio, an increase in CD4 and CD8 double-negative T cells, and an increase in immature T cells in the peripheral circulation." (PMID 40507146, 2025). "However, the specific etiology of the leukopenia is unknown, and this mechanism does not explain the selective decrease in peripheral naïve CD4+ T cells." (PMID 35062255, 2021). "A transient leukopenia was found due to the reduction in all CD3+, CD4+, and CD8+ T lymphocytes, CD21+ B lymphocytes, and NK cells at 3- and 4-days post-infection without any variation in the CD4:CD8 ratio and in the number of B lymphocytes." (PMID 39858163, 2025). "Severe PEM provokes atrophy of thymus as well as peripheral lymphoid organs, which in turn reduces cell number (leukopenia), decreases CD4/CD8 ratio, increases numbers of CD4 and CD8 double-negative T cells, and increases the number of immature T cells in the peripheral blood." (PMID 29093710, 2017).
mycosis fungoides (71 papers, 2004 to 2025). Classical mycosis fungoides is the most common type of mycosis fungoides (MF), a form of cutaneous T-cell lymphoma, and is characterized by slow progression from patches to more infiltrated plaques and eventually to tumors. "The most common subtype, mycosis fungoides (MF), and its more aggressive leukemic variant, Sézary syndrome (SS), originate from monoclonal proliferation of T-lymphocytes, typically CD4+ T-cells with a predilection for the skin." (PMID 40940819, 2025). "The initial biopsy revealed features consistent with plaque-stage mycosis fungoides, characterized by CD4 predominance, CD7 deficiency, and a low Ki-67 index (< 5%)." (PMID 41174711, 2025). "Four patients reported a previous history of early stage mycosis fungoides (MFs) lasting a median of 36 months (range 28–48): one of the classic CD4+ variant, two of the folliculotropic CD4+ variant, and one of the CD8+ variant with folliculotropism." (PMID 34842638, 2021). "Etiopathogenic, mycosis fungoides is characterized by the proliferation of lymphocytes that express the T-cell receptor (CD4+) on the surface, causing increased production of Th2-type cytokines, with indolent evolution and favorable prognosis when diagnosed in the early stages of the disease." (PMID 35573524, 2022). "Mycosis fungoides (MF) is a low-grade chronic lymphoid proliferative disorder of T-lymphocytes arising out of the skin, having an indolent course caused by abnormal proliferation of CD4+ T-cells." (PMID 35106236, 2021). "FMF is a rare distinct clinicopathologic variant of mycosis fungoides (MF), characterized by infiltration of atypical CD4+ T cells with folliculotropism, often with minimal or absent epidermotropism." (PMID 40981346, 2025). "LyP Type B is characterized by wedge-shaped or band-like epidermotropic infiltration of CD4-positive small-to medium-sized pleomorphic cells in the dermis, with tumor cells resembling the gyrate lymphocytes of mycosis fungoides." (PMID 40666517, 2025). "The early diagnosis suggested tumor-stage mycosis fungoides, based on histopathology and immunophenotype (CD4+, CD20-)." (PMID 40918840, 2025). "Mycosis fungoides (MF) and Sézary syndrome (SS) are the most prominent subtypes and typically stem from malignant mature CD4+ helper T cells." (PMID 40861896, 2025). "Mycosis fungoides was CD4+ in 50 cases (44.6%) and CD8+ in 35 cases (31.2%); however, in 27 cases no T-cell immunohistochemical profile information was obtained." (PMID 38395632, 2024). "For example, mycosis fungoides, which is a type of cutaneous T-cell non-Hodgkin's lymphoma, is characterized by the abnormal accumulation of CD4 + T cells in the skin." (PMID 38280109, 2024). "Mycosis fungoides (MF) and the leukemic variant Sézary syndrome (SS) comprise the most common types of cutaneous T cell lymphomas (CTCLs) that develop from skin-homing clonally expanded CD4+ T cells in a background of chronic inflammation." (PMID 37427589, 2023). "In summary, this long-term experiment confirmed that Socs1-knockout in skin-resident CD4+ T cells in a protracted contact-allergic reaction results in an autonomous skin inflammation with features of early-stage mycosis fungoides." (PMID 37664523, 2023). "Overall, cases of CD8+ mycosis fungoides are less common and relatively less understood than their CD4+ counterparts, with varied presentations and courses." (PMID 36547219, 2022). "Mycosis fungoides (MF) is the most frequent subtype of skin T-cell lymphoma with monoclonal proliferation of neoplastic CD4+ T cells in the skin." (PMID 35237320, 2022). "Using multispectral fluorescent imaging, we show that the progression of mycosis fungoides from plaque to tumor parallels the cutaneous expansion of the malignant CD4+ T cells that express TOX." (PMID 34885092, 2021).
mycosis fungoides (continued). "Mycosis fungoides (MF), characterized by a monoclonal proliferation of CD4‐positive T cells, is the most common type of cutaneous T‐cell lymphoma (CTCL) and constitutes almost 50% of all primary cutaneous lymphomas." (PMID 34480528, 2021). "Mycosis fungoides (MF) is the most common cutaneous T-cell lymphoma (CTCL) derived from CD4+ T-cells." (PMID 34204115, 2021). "Mycosis fungoides (MF), the most common form of primary cutaneous lymphoid malignancy, is typically characterized by an infiltration of neoplastic CD4-positive T lymphocytes in the skin." (PMID 34831413, 2021). "Although Mycosis Fungoides is the most common form of CD4-positive CTCL, it is prudent to consider PTL-NOS as the initial diagnosis for such a presentation, bearing in mind the rarity of the disease and nonspecific immunohistochemical analysis." (PMID 26380134, 2015). "CTCL covers a range of diseases, including mycosis fun-goides (MF) and Sézary syndrome, characterized by infiltration of malignant T cells that express CD4 into the skin." (PMID 18702090, 2008). "Thus, we clearly demonstrate that mice with one-copy deletion of Socs1 in skin resident CD4+ T cells in protractedly inflamed skin lead up to an autonomous inflammation and the features of early-stage mycosis fungoides." (PMID 37664523, 2023). "CD4+ lymphocytes were the predominant subtype among all stained tissue sections, which is in accordance with the classical predominance of the helper/inducer phenotype in mycosis fungoides (CD3+, CD4+, CD8−)." (PMID 36428999, 2022). "Mycosis fungoides (MF) is the most common form of CTCL characterized by skin-homing CD4+ T cells." (PMID 32477957, 2020). "Similarly, the most common form of cutaneous T-cell lymphoma—mycosis fungoides—is characterized by focal plaques and tumors of poorly controlled malignant CD4+ T cells, in which CD7− status correlates with resistance to Gal1-induced apoptosis." (PMID 29463785, 2018). "Since double positive CD4/CD8 phenotype is rarely reported in mycosis fungoides the presence on conventional immunophenotyping of both CD may be due to a “mixture” of neoplastic cells and inflammatory CD8+ tumor infiltrating lymphocytes." (PMID 25143835, 2014). "Mycosis fungoides (MF) classically presents with a CD4+/CD8- immunophenotype at the time of diagnosis." (PMID 40166794, 2025). "Mycosis fungoides (MF) is a cutaneous T-cell lymphoma (CTCL) that is characterized by atypical CD4+ T-cell aggregates in the epidermis." (PMID 39165452, 2024). "Mycosis fungoides (MF) is characterized by the proliferation of malignant mature skin resident CD4+ T cells." (PMID 37664523, 2023). "Mycosis Fungoides (MF) and Sézary syndrome (SS), accounting for 65% of all CTCLs, are characterized by the clonal expansion of skin resident CD4+ T cells." (PMID 36649072, 2023). "Regarding CTCL, the most common histology was mycosis fungoides/Sézary syndrome (MF/SS, N = 14) followed by primary cutaneous anaplastic large cell lymphoma (pcALCL, N = 6) and CD4+ small/medium cell primary cutaneous lymphoma (pcSMPTCL, N = 5)." (PMID 29515769, 2018). "In contrast, KIR3DL2 expression is found in several CD4+ T malignancies, including SS, mycosis fungoides (MF) and anaplastic large cell lymphoma (ALCL)." (PMID 29387053, 2017). "However the double positive CD4/CD8 phenotype is extremely rare in mycosis fungoides." (PMID 25143835, 2014). "The subgroup of Mycosis fungoides (MF), which is a T-cell lymphoma primarily of the skin and originating from CD4-positive T-helper cells, accounts for approximately 38% of cases." (PMID 22838493, 2012). "Mycosis fungoides (MF) and Sézary syndrome (SS) are the most common types of cutaneous T-cell lymphomas and represent clonal proliferations of neoplastic CD4+ T cells." (PMID 22162690, 2011). "Mycosis fungoides (MF) and Sézary syndrome (SS) are two types of cutaneous T-cell lymphoma (CTCL) characterized by pathological CD4+ T-cells." (PMID 40427608, 2025).